GSK3B (glycogen synthase kinase 3 beta)
Diseases named in the same sentence as GSK3B in open-access papers (continued):
Sharing a sentence is not in itself a finding about the gene and the disease.
gastric cancer (continued). "In gastric cancer (GC), the transient receptor potential canonical 3 (TRPC3) promotes tumorigenesis via the CNB2/GSK3β/NFATc2 signaling pathway; thus, TRPC3 could be a possible target for therapeutic intervention." (PMID 39822413, 2024). "In gastric cancer, AKT/GSK-3β/β-catenin signaling is upregulated in IGHG1 cells." (PMID 36883223, 2023). "IGHG1 overexpression has also been reported for the induction of epithelial to mesenchymal cell transmission (EMT) in gastric cancer via tumor growth factor beta (TGF-β)/SMAD3 signaling, whilst AKT/glycogen synthase kinase 3 beta (GSK-3β)/β-catenin pathway is also highly active." (PMID 36883223, 2023). "In summary, our study shows that UFM1 may downregulate the expression level of PDK1, which inhibit the AKT/GSK3β pathway and downregulating the EMT activity of gastric cancer cells, leading to suppress the invasion and metastasis of gastric cancer cells." (PMID 31533855, 2019). "Targeting the key factors in the β‐catenin signaling pathway, including β‐catenin, GSK3β, and LRP6, could counteract M hyorhinis‐induced gastric cancer cell motility." (PMID 31321908, 2019). "Our previous study demonstrated that CDK5RAP3 expression was downregulated in gastric cancer, which correlated with poor prognosis, and that CDK5RAP3 could inhibit Wnt/β-catenin signaling by blocking GSK-3β phosphorylation at Ser9." (PMID 29540196, 2018). "Although CDK5RAP3 has been shown to negatively regulate the Wnt/β-catenin signaling pathway in gastric cancer by repressing GSK-3β phosphorylation, its in-depth mechanism has not been determined." (PMID 29540196, 2018). "In addition, NKX6.3 induced β-catenin binding to the β-catenin destruction complex, including GSK3β, Axin1, APC, and β-Trcp, in NKX6.3 stable gastric cancer cells." (PMID 27333045, 2016). "Resveratrol inhibited PI3K and Akt phosphorylations, and subsequently triggered the dephosphorylation of glycogen synthase kinase 3 beta (GSK3β), which resulted in cyclin D1 degradation and eventually cell cycle arrest and apoptosis in MGC803 human gastric cancer cells." (PMID 28119606, 2016). "Consequently, in the present study, the direct role of IGF-I in promoting EMT in gastric cancer and the role of the PI3K/Akt signaling pathway, GSK-3β and ZEB2 in this process was investigated." (PMID 25435948, 2015). "By exploring the correlation between lnc-CHAF1B-2 and key proteins in Wnt/β-catenin D1, which correspond to the genes CTNN GSK3B and CCND1, we hypothesized that lnc-CHAF1B-2 might promote the development and progression of gastric cancer through activation of the Wnt/β-catenin pathway." (PMID 39747989, 2025). "Interestingly, an immunoprecipitation assay with a PD4 antibody against the p37 protein detected a complex containing p37 and two upstream regulators of β‐catenin signaling, including GSK3β and the Wnt receptor LRP6,16, 17, 18 in M hyorhinis‐infected gastric cancer cells." (PMID 31321908, 2019). "There have been many breakthroughs regarding the upstream regulatory mechanisms of AKT; however, whether AKT/GSK-3β/β-catenin signaling is regulated by CDK5RAP3 in gastric cancer has not been explored." (PMID 29540196, 2018). "In gastric cancer inhibition of MTDH may decrease the level of β-catenin and inactivate Wnt/β-catenin pathway through reducing phosphorylation of AKT and glycogen synthase kinase (GSK)-3β (Ser 9)." (PMID 22768080, 2012). "Although further investigations are needed to clarify the molecular mechanisms involved in GSK-3β activation, the present findings suggest that GSK-3β activation plays an important role probably via inhibition of cell cycle progression, and is a candidate prognostic biomarker in gastric carcinoma." (PMID 20704706, 2010). "Thus, our findings suggest that cyclin D1 expression in gastric cancer cells might be regulated by signaling molecules such as Ras, Nuclear factor-κB or β-catenin rather than GSK-3β as previously reported." (PMID 20704706, 2010).
glioma (146 papers, 2008 to 2026). A benign or malignant brain and spinal cord tumor that arises from glial cells (astrocytes, oligodendrocytes, ependymal cells). "Recent publications suggest that gliomas deficient for the tumor suppressor PTEN show a strong inhibition of GSK-3β, which in turn induces the expression of galectin Gal9." (PMID 40157890, 2025). "Wnt/β-catenin and ERK/GSK3β signaling pathways were closely associated with cell proliferation and progression in glioma." (PMID 35978634, 2022). "Although our results showed a relatively low proportion of CNA, previous research on human glioma cell culture showed that GSK3β inactivation by point mutations and phosphorylation existed in 67% of glioma samples." (PMID 34209611, 2021). "In this report, we investigated the effects of CKIP-1 on glioma cells and explored the molecular mechanisms behind the growth-suppressive activity of CKIP-1 associated with GSK-3β in glioma cells." (PMID 31355268, 2019). "Although it was pointed out previously that GSK-3β dysregulation was associated with glioma genesis and progression, the function of CKIP-1 and the relationship between CKIP-1 and GSK-3β in glioma remained to be elucidated." (PMID 31355268, 2019). "Mdm2 and Crem are associated with glioma, leukemia, prostate cancer, chronic myeloid leukemia, and several other cancer pathways, whereas, Gsk3b is an antitumor gene associated with prostate cancer." (PMID 31523185, 2019). "GSK3β has been linked to glioma invasion ability 26 and its inhibition leads to an increase in glioma sensitivity to Temozolomide 27 and to radiotherapy." (PMID 27641066, 2017). "In this study, we applied tissue microarray technique to detect a significant increase of p-GSK3β-Ser-9 levels in most glioma tissues, which is associated with patients with high-grade gliomas and metastatic tumors." (PMID 26388612, 2015). "PI3K/Akt, and the Akt downstream target GSK3β, have been implicated in actin filament remodeling and cell migration in several cell types, including glioma cells." (PMID 25268128, 2014). "In addition, LiCl inhibits the cell proliferation of C6 glioma cells harboring an IDH2 (isocitrate dehydrogenase-2) mutation via GSK3β." (PMID 36836894, 2023). "In vitro cell co-culture experiments, intracranial co-injection tumorigenesis assay, and RNA-seq suggest MS4A7-s promotes activation of glioma-associated macrophages’ (GAMs) PI3K/AKT/GSK3β pathway, leading to M2 polarization, and drives malignant progression of GBM." (PMID 36944954, 2023). "The PI3K/Akt/GSK-3β signaling pathway plays a critical role in regulating glioma cell proliferation, stemness maintenance, and tumor growth." (PMID 41141394, 2026). "Taking together, we identify a novel signaling pathway-WNT3A/CELSR2/GSK-3β/β-catenin in the development of gliomas." (PMID 41184253, 2025). "We conducted an in silico analysis integrating publicly available data from scRNAseq studies of non-tumoral brain and gliomas with a focus on the analysis of PDE7 and GSK-3β expression in gliomas." (PMID 40157890, 2025). "Mechanistically, Res modulates the Akt/GSK-3β/NF-κB axis, contributing to reduced proliferation and enhanced apoptosis in glioma cells." (PMID 40802352, 2025). "Sohlh1 inhibited the proliferation, migration and invasion of glioma cells through upregulation of GSK‐3β expression." (PMID 40418209, 2025). "A Wnt5a knockdown inhibited the activity of the GSK3β/β-catenin pathway related to glioma-derived endothelial cell angiogenesis." (PMID 41031155, 2025). "Given the ubiquitous expression of GSK-3β in gliomas, we cannot exclude a direct effect of this molecule on the phenotype of the glioma-associated macrophages." (PMID 40157890, 2025).
glioma (continued). "In contrast, genistin inhibited the pathway in glioma U-87 cells, decreased the levels of Wnt1 and Wnt3a, and increased the p-GSK3β/GSK3β ratio." (PMID 40427472, 2025). "Together with the fact that the predominant isoform GSK3B is upregulated in IDHmut glioma (CGGA) and astrocytes, these findings in combination with our data support the notion that GSK3 signaling plays an important role during IDHmut gliomagenesis." (PMID 40307935, 2025). "In our study, Phosphodiesterase 2A (PDE2A) was up-regulated, a gene known to suppress Wnt/β-catenin signaling in glioma stem-like cells by modulating cAMP accumulation and GSK-3β phosphorylation." (PMID 39874307, 2025). "In this study, we found that recombinant highly phosphorylated tau purified from NG108-15 rodent neuroblastoma/glioma cells transfected with both tau and GSK3β expression vectors bound calcium ions and formed sarkosyl-insoluble aggregates." (PMID 39655264, 2024). "Our previous studies suggested that Chr-A downregulates protein kinase B (Akt)/glycogen synthase kinase 3 β (GSK-3β) and the downstream c-Myc to inhibit the growth of glioma cells in vivo and in vitro." (PMID 39330272, 2024). "YAP has been reported to promote glioma cell proliferation by regulating the expression, subcellular localization, and transcriptional activity of β-catenin through GSK3β." (PMID 38547301, 2024). "GSK-3β signaling is also proposed as a potential therapeutic target for regulating angiogenesis in human glioma cells." (PMID 39707578, 2024). "It has been reported that IFI30 can promote the EMT process in glioma cells by activating EGFR/AKT/GSK3β/β-catenin." (PMID 38517387, 2024). "GNG12 belongs to the G protein family, and GNG12-AS1 stimulates or suppresses the proliferation and relocation of glioma cells by influencing the KT/GSK-3β/β-catenin pathway activity." (PMID 39707577, 2024). "From this, it was evident that our triple-drug combination significantly reduced glioma proliferation by inhibiting the Nrf2/HIF-1α-mediated PI3K/GSK3β signalling pathway." (PMID 37025487, 2023). "Mast cells suppress the signal transducer and activator of transcription 3 (STAT3) pathway by downregulating glycogen synthase kinase 3β (GSK3β), thereby diminishing the proliferation, migration, and invasion of glioma cells." (PMID 37662954, 2023). "The proto-oncogene AEG-1, overexpressed in gliomas, is targeted to GSK-3β (glycogen synthase kinase-3β) to activate the Wnt/β-catenin pathway, mediating a pro-tumor phenotypic shift in microglia and reducing the sensitivity of glioma cells to TMZ." (PMID 37700840, 2023). "Their results showed that FAM84B plays an important role in the proliferation, invasion, and apoptosis of glioma cells by affecting the Akt/GSK-3β/β-catenin pathway." (PMID 36419094, 2022). "Inactivation of glycogen synthase kinase (GSK)3β through serine 9 phosphorylation following CD95/CD95L interactions has been reported to mediate invasion in long-term glioma cells." (PMID 35906203, 2022). "BYSL also reportedly promotes glioma/glioblastoma growth via the GSK-3β/β-catenin and AKT/mTOR pathways." (PMID 35508466, 2022). "Studies suggested that Axin expression was downregulated in glioma cells, and the activation of GSK3β can promote the proliferation and differentiation of glioma cells." (PMID 35497928, 2022). "WNT5A/GSK3β/β-catenin signaling played a pivotal role in the angiogenesis of glioma-derived endothelial cells." (PMID 35494062, 2022). "Taken together, our results demonstrate that quercetin inhibited migration and invasion of human glioma cells by suppressing GSK3β/β-catenin/ZEB1 signaling." (PMID 36386155, 2022). "Western blot results showed that overexpression of Rab23, LCA alone, and combined treatment can downregulate β-catenin and c-myc protein levels in glioma U251 cells, which can upregulate GSK3β and Axin2 protein levels." (PMID 35497928, 2022).
glioma (continued). "Loss of WBSCR22 can decrease the phosphorylation of AKT and GSK3β, which also destabilize the intracellular levels of CCND1 and β-catenin, thus inhibiting glioma progression." (PMID 35590385, 2022). "This study showed that AEG-1 silencing inhibits Wnt/β-catenin signaling by targeting GSK-3β in glioma cells." (PMID 34462446, 2021). "The co-localization of AEG-1 and GSK-3β in the cytoplasm of glioma cells was detected through immunofluorescence staining." (PMID 34462446, 2021). "Lithium chloride (LiCl, a GSK-3β inhibitor) was reported to reduce invasion rates in the U87 glioma line while increasing β-catenin activity." (PMID 34577571, 2021). "We also report that YAP/TAZ is up-regulated in gliomas and YAP promotes glioma progression by inhibiting GSK3β and then activating β-catenin." (PMID 33726796, 2021). "In gliomas, GSK-3β is downregulated; its overexpression inhibits angiogenesis and tumor growth by upregulating the β-catenin and mTOR/p70S6K1 pathways, and also restores cell differentiation." (PMID 34887392, 2021). "LncRNA AC023115.3 induced by chemotherapy, in turn, improves chemosensitivity of glioma to cisplatin by competing with miR-26a, thereby releasing GSK3β to inhibit autophagy." (PMID 34671362, 2021). "CD163 is also involved in regulating the role of CK2 in glioma stemness by interacting with CK2β, leading to an increase in phosphorylation of AKT, GSK-3β/β-catenin pathway activity, inappropriate cell cycle progression, and glioma proliferation." (PMID 34680478, 2021). "It has also been demonstrated that GSK3β inhibition suppresses glioma cell migration and invasion by reducing cell polarity." (PMID 34475984, 2021). "The accumulated co-localization of AEG-1 and GSK-3β mainly in the cytoplasm of glioma cells was detected by immunofluorescence staining." (PMID 34462446, 2021). "Interactively, recruited MCs release a variety of mediators to inhibit glioma progression and induce tumor differentiation by downregulating GSK3β expression." (PMID 34671362, 2021). "Here, we found that the elevated CD147 in glioma cells suppressed GSK-3β activity, which in turn blocked SCF/β-TrCP mediated Nrf2 protein degradation." (PMID 34421346, 2021). "Taken together, these results indicated that FTL promoted EMT of glioma cells by regulating AKT/GSK3β/β-catenin signaling." (PMID 32677981, 2020). "Our study demonstrated that GNG12-AS1 promoted proliferation and migration of glioma cells through activating the AKT/GSK-3β/β-catenin signaling pathway." (PMID 32735016, 2020). "Studies have shown that RNCR3 can activate the Akt/GSK3β signaling pathway in gliomas to exert its cancer-promoting effect, so we verified the effect of RNCR3 on the Akt/GSK3β signaling pathway in HCC." (PMID 33062024, 2020). "FTL promoted EMT of glioma by regulating AKT/GSK3β/ β-catenin signaling, which subsequently enhanced invasion and chemoresistance of glioma cells." (PMID 32677981, 2020). "A recent report indicates that transfection with shRNA targeting GSK3α in U87 and A172 glioma cells upregulates GSK3β activity and results in increased levels of c-myc, pERK1/2 (Thr202/Thr204), and cyclin D1." (PMID 33339170, 2020). "Taken together, we demonstrated that hypoxia induced FTL promoted EMT by regulating AKT/GSK3β/β-catenin signaling, which subsequently enhanced invasion and chemoresistance of glioma cells." (PMID 32677981, 2020). "Silencing OIP5-AS1 reduced cell proliferation, invasion and migration of glioma U87 cells and led to depressed expression levels of miR-410, Wnt-7b, p-β-catenin, GSK-3β-pS9, c-Myc and cyclin D1." (PMID 30498093, 2019). "In this study, our results verified the interaction between CKIP-1 and AKT and the effects of CKIP-1 on AKT/GSK3β/β-catenin signaling pathway in glioma cell." (PMID 31355268, 2019). "We then used the IHC method to analyze and score CKIP-1 and AKT/GSK3β/β-catenin proteins in normal brain tissue and patient glioma tissues." (PMID 31355268, 2019).
glioma (continued). "Previous reports demonstrated that GSK3β inhibitors suppress glioma stem cell properties via down-regulation of SOX228,29." (PMID 31296906, 2019). "Our results also showed that upregulation of CKIP-1 inhibits the proliferation of human glioma cell line via suppression of AKT/GSK3β/β-catenin signaling pathway." (PMID 31355268, 2019). "In our previous experiments we found that CKIP-1 and glycogen synthase kinase-3β (GSK-3β) were all low expressed in human glioma U251 cells and human glioma tissues." (PMID 31355268, 2019). "First, we found that SPHK2 overexpression increased phosphorylated Akt, phosphorylated GSK3-β and β-catenin levels, whereas SPHK2 inhibition decreased phosphorylated Akt, phosphorylated GSK3-β, and β-catenin levels in glioma cells." (PMID 31171769, 2019). "Research indicates that the up-regulated transcription factor E2F1 and glycogen synthase kinase-3β (GSK-3β, an intact complex of E2F1) in astrocytomas and GBM were associated with the progression of glioma and correlated with LSH expression." (PMID 30498431, 2018). "In the current study, we showed the differential expression of the downstream GSK-3β and elF2α in glioma cell lines." (PMID 29301329, 2018). "Lipoprotein receptor-related protein 6 (LRP6), an upstream regulator of GSK3β signaling pathway, was also over expressed in glioma tissue." (PMID 30498431, 2018). "Taken together, a mechanistic link between LSH expression and activation of the LPR6/GSK3β/E2F1 axis in glioma illustrates a novel role of LSH in malignant astrocytomas and GBM." (PMID 30498431, 2018). "We found that the overexpression of RASD1 remarkably suppressed the phosphorylation of AKT (Thr308), GSK3β and S6 ribosome protein in glioma cells." (PMID 28600528, 2017). "A previous study showed a reversible dose-dependent effect of lithium on attenuation of glioma cell invasion via inhibition of GSK3β activity." (PMID 28423558, 2017). "The results showed that the expression levels of p-GSK-3β (Ser9) are significantly up-regulated in glioma tissues compared with normal tissues." (PMID 26388612, 2015). "On the other hand, inhibition of GSK3β activity results in c-MYC dependent glioma cell death through multiple mechanisms, all of which converge on the apoptotic pathways." (PMID 26437223, 2015). "Our study shows that there is a strong expression of total GSK-3β in the vast majority of normal and glioma tissues." (PMID 26388612, 2015). "Glioma cells over-expressing GSK-3β were used to analyze biological functions both in vitro and in vivo." (PMID 26388612, 2015). "To explore the functional relevance of GSK-3β in glioma, we utilized U87 cells infected with adenovirues carrying GSK-3β (Ad-GSK-3β)." (PMID 26388612, 2015). "Glioma specimens and normal brain tissues were analyzed for the expression levels of GSK-3β and p-GSK-3β (Ser9) by tissue microarray analysis (TMA) and Western blotting." (PMID 26388612, 2015). "Higher p-GSK-3β (Ser9) expression levels were detected in 60 (67%) of 90 glioma cases, and were significantly correlated with higher glioma grade." (PMID 26388612, 2015). "In order to get an insight into the biological relevance of GSK-3β in glioma, we did immunohistochemical stainings and Western blotting analysis of total GSK-3β and phospho-GSK3β at Ser-9 levels in glioma tissues." (PMID 26388612, 2015). "Further investigations are needed to reveal resolve the relationship between these two signaling pathways in the context of GSK-3β-inhibited glioma development." (PMID 26388612, 2015). "The expression levels of β-catenin were higher in glioma tissues compared to the normal tissues, and were decreased following ectopic expression of GSK-3β in U87 and U251 cells." (PMID 26388612, 2015). "Forced expression of GSK-3β in glioma cells significantly inhibited both tumor growth and angiogenesis in vivo." (PMID 26388612, 2015).